ATG7 (autophagy related 7)
Diseases named in the same sentence as ATG7 in open-access papers (continued):
Sharing a sentence is not in itself a finding about the gene and the disease.
liver cancer (14 papers, 2019 to 2025). An epithelial or non-epithelial malignant neoplasm that arises from the liver. "At the same time, many studies in genetically engineered mice have confirmed that the deletion of the At96/Beclinl allele of autophagy regulatory gene induces liver cancer, and the deletion of Atg5 or Atg7 can also cause liver cancer in mice." (PMID 37038623, 2023). "In conclusion, TINCR reduces miR-375 expression in liver cancer cells, which lowers ATG7 to limit cell proliferation and invasion." (PMID 36157234, 2022). "The results indicated that overexpressing lncRNA TINCR (vector-TINCR) in liver cancer SMMC-7721 cells significantly increased ATG7 expression compared to the vector control group (vector-control)." (PMID 36157234, 2022). "Overall, our work provided evidence that the lncRNA TINCR controls the growth and invasion of liver cancer cells through the miR-375/ATG7 signaling pathway." (PMID 36157234, 2022). "Functional experiments demonstrated that knocking down lncRNA TINCR significantly inhibited ATG7 expression in liver cancer cells, while transfecting miR-375 mimics significantly blocked this effect." (PMID 36157234, 2022). "Experiments on cell function showed that lncRNA TINCR regulates miR-375/ATG7, which in turn influences liver cancer cell proliferation and invasion." (PMID 36157234, 2022). "Western blotting was used to investigate the role of miR-375 in the regulation of ATG7 expression by lncRNA TINCR in liver cancer cells." (PMID 36157234, 2022). "ATG7 knockdown prevents tumorigenesis in a mouse liver cancer model." (PMID 37790613, 2023). "To test more directly whether TAZ is degraded by autophagy, we first deleted ATG7 or ATG5 expression in the liver cancer cell lines HLE and Huh7 using the CRISPR-Cas9–mediated gene disruption system." (PMID 34088666, 2021). "Therefore, the lncRNA TINCR/miR-375/ATG7 signaling axis could be a novel biological target for the diagnosis and therapy of liver cancer." (PMID 36157234, 2022). "Therefore, bioinformatics algorithms indicated that miR-375 may bind to the downstream target gene ATG7 in liver cancer cells." (PMID 36157234, 2022). "Therefore, resistance of the liver-specific Atg7-knockout mice to progress from benign adenoma to liver cancer might be due to persistent expression of NCoR1." (PMID 31879337, 2020). "SMAD2 and SMAD3 correlated with autophagy-related scores (based on ATG12, ATG7, ATG3, ATG5, ATG4B, PIK3C3, PRKAA2, and GABARAPL1) in liver cancer." (PMID 37790613, 2023). "By controlling the miR-375/ATG7 axis, the lncRNA TINCR impacts the proliferation and invasion of liver cancer cells." (PMID 36157234, 2022). "Given the variables’ relationship with the OS of liver cancer patients, we further examined the roles of all five variables, TIPRL, LC3 (ATG7), CD133, CD44, and CD46, in normal liver (Chang), HCC (huh7), and iCCA (SNU1097) cell lines." (PMID 34208132, 2021). "The compound does not cause apoptotic death in liver cancer cell lines; instead, it induces cell death through autophagy, as evidenced by increased levels of ATG5, ATG7, beclin, and BNIP, and the induction of the LC3-I to LC3-II conversion." (PMID 39275166, 2024). "In mice with knockout of core autophagy proteins, ATG5 and ATG7, the absence of these proteins leads to autophagy-defective hepatocytes that develop liver cancer due to mitochondrial damage and oxidative stress." (PMID 39349421, 2024). "Luciferase reporter and Western blotting showed that lncRNA TINCR regulates the expression of ATG7 through miR-375, and the rescue experiment proved that lncRNA TINCR controls the invasion and proliferation of liver cancer cells via the miR-375/ATG7 signaling pathway." (PMID 36157234, 2022).
liver cancer (continued). "Given this significant correlation between levels of TIPRL, LC3 and CD133 in HCC tissues, we investigated and observed significant reductions in TIPRL, LC3, ATG7, CD133 and CD46 mRNA levels in HCC/liver cancer cell-lines transfected with two different small interfering RNA against TIPRL (siTIPRL)." (PMID 31727942, 2019). "Moreover, mice lacking Atg5 or Atg7 have been reported to develop liver cancers." (PMID 35054896, 2022).
liver fibrosis (14 papers, 2016 to 2025). "We used hepatocyte-specific Atg7-knockout mice to investigate the association between autophagy and liver fibrosis." (PMID 32120837, 2020). "Specific deletion of Atg7 in mouse HSCs could attenuate chronic injury-induced liver fibrosis, which was associated with autophagy-mediated lipid metabolism." (PMID 31614437, 2019). "Thus, there is still a substantial gap between the current understanding of the potential roles of autophagy deficiency in the progression of liver fibrosis and whether Atg5 and Atg7 can be used as effective targets for the treatment of liver diseases." (PMID 32724454, 2020). "Blocking autophagy in hematopoietic stem cells using 3-methyladenine, doxazosin or specific siRNA targeting ATG5 and ATG7 resulted in reduced activation of HSCs and attenuation of liver fibrosis." (PMID 40406118, 2025). "The authors also reported that HSC‐specific deletion of Atg7 attenuated mice liver fibrosis induced by CCl4 or thioacetamide." (PMID 33438347, 2021). "In a mouse model of hepatic fibrosis induced by CCl4 or thioacetamide, knocking out the key autophagy protein Atg7 can alleviate the level of liver fibrosis." (PMID 32872238, 2020). "Further, autophagy markers, notably microtubule-associated protein 1 light chain 3B (LC3B), ATG12-5, and ATG7 were significantly upregulated in the livers of cirrhotic patients and in 2-acetylaminofluorene (AAF)/CCl4-induced liver fibrosis in rat." (PMID 27313533, 2016). "In experimental mouse models of CCl4-induced liver fibrosis, autophagy-related protein 7 (ATG7), fibrogenesis, and ECM accumulation were found to be remarkably reduced, but this finding could not be replicated in cultured HSCs by adding exogenous fatty acids." (PMID 39063116, 2024). "Taken together, these data suggest that deletion of ATG7 promotes hepatic fibrosis in mice." (PMID 36078110, 2022). "BBR downregulated ATG5 and ATG7 expression with a decrease in α-SMA in HSCs, which is consistent with the double IF staining in mouse liver fibrosis." (PMID 34864819, 2021). "On the other hand, XBP1 regulates liver fibrosis via the transport and Golgi organization-1 (TANGO1)-collagen axis and the regulation of ATG7-dependent autophagy in hepatic stellate cells." (PMID 34209019, 2021). "One study demonstrated that miR-96-5p inhibits the activation of HSCs by regulating ATG7 to block autophagy, and another demonstrated that fucoidan can inhibit ECM deposition and autophagy in liver fibrosis." (PMID 33488687, 2020). "Impaired autophagy by deletion of Atg7 in endothelial cells did not affect liver homeostasis but amplified liver fibrosis without increasing liver injury following CCL4-treatment." (PMID 31614437, 2019). "Both 3-MA, a chemical inhibitor of autophagy, and transfection with siRNAs targeting Atg3 and Atg7 inhibited autophagy in HSCs and in the livers of CCL4- or TAA-treated mice and reduced lipid metabolism and energy production, which then inhibited ECM production and liver fibrosis." (PMID 32724454, 2020).
Parkinson disease (14 papers, 2008 to 2025). A progressive degenerative disorder of the central nervous system characterized by loss of dopamine producing neurons in the substantia nigra and the presence of Lewy bodies in the substantia nigra and locus coeruleus. "Although no direct links between ATG7 dysfunction and neurodegeneration have been demonstrated, polymorphisms within the ATG7 promoter region have been suggested to contribute to sporadic Parkinson’s disease, yet their impacts on promoter activity were modest." (PMID 34725936, 2021). "Furthermore, IRE1 was able to promote dopaminergic neuron loss, progressive locomotor impairment, and shorter lifespan, whereas blocking IRE1 or ATG7 expression remarkably ameliorated the progression of α-synuclein-caused Parkinson’s disease." (PMID 31641108, 2019). "In five patients with Parkinson’s disease, four novel genetic variants including 11313449G>A, 11313811T>C, 11313913G>A, and 11314041G>A, were identified on the ATG7 gene promoter, implying the altered transcriptional activity of the ATG7 may be a risk factor." (PMID 26404030, 2015). "Moreover, genetic variants were identified in the ATG7 gene promoter of patients with Parkinson’s disease, suggesting that altered transcriptional activity of ATG7 may be a risk factor." (PMID 31450711, 2019). "In fact, SNPs in ATG5 and ATG7 are linked to the development of neurological disorders such as cerebral palsy (both ATG5 and ATG7), Huntington’s disease (ATG7), and Parkinson’s disease or spinocerebellar ataxia (ATG5)." (PMID 33147747, 2020). "Sequence variants affecting the expression levels of ATG12 (115842507G>T, 115842394C>T and 115841817_18del) and ATG7 (11313449G>A, 11313811T>C, 1313913G>A and 11314041G>A) are present in patients with sporadic Parkinson’s disease." (PMID 33147747, 2020). "Of these, particular genes of interest include ATG7, which has been associated with frontotemporal dementia; TUSC3, a gene associated with intellectual disability; and PARK2, a gene associated with Parkinson’s disease." (PMID 25887117, 2015). "CGA also modulated the expression of genes related to Parkinson’s disease and autophagy, including α-synuclein (α-syn), LC3B, SQSTM1, ATG5, ATG7, and ULK1B, thereby indicating its capacity to enhance autophagy in Parkinson’s disease pathogenesis." (PMID 41142236, 2025). "Although tau pathology was not investigated in these other models, staining for the Parkinson’s disease associated proteins α-synuclein and leucine rich repeat kinase-2 (LRRK2) was reported in Atg7-deficient DA neurons." (PMID 22998728, 2012).
steatosis (14 papers, 2015 to 2025). Increased lipid within the cytoplasm of cells. "Similar to a previous study by using siRNA knockdown Atg7, mice with inducible deletion of Atg7 in the liver are more susceptible to alcohol-induced liver injury and steatosis." (PMID 31614437, 2019). "Within fasting-induced steatosis models, we analyzed 11 experiments from 10 manuscripts that used genetic liver-specific KO models for ATG7, ATG5, TFEB, and FIP200." (PMID 33937257, 2021). "In line with it, ATG7-overexpression successfully reversed hepatic LD accumulation and prevented steatosis in obese mice." (PMID 34777688, 2021). "Within nutrient overload steatosis models, 13 different experiments were analyzed from 9 manuscripts which genetically modulated the expression of ATG7, ATG4B, ATG14, TFEB, FIP200, and ULK1." (PMID 33937257, 2021). "Mice with a liver-specific deletion of Atg7 were also protected from PEG-asparaginase-induced weight loss and displayed a blunted transcriptional execution of the ISR in the liver alongside reduced steatosis." (PMID 39798881, 2025). "Moreover, autophagy enhancement in obese mice via Atg7/Atg14 overexpression alleviated the steatosis extent." (PMID 34777688, 2021). "Although Pten-deficient livers develop steatosis and HCC, we observed that hepatic Pten deletion alone did not initiate liver damage, inflammation, hepatic stellate cell activation, fibrosis, or a ductular reaction in young livers, but these effects were observed on hepatic deletion of ATG5 or ATG7." (PMID 34088666, 2021). "While results with Atg7-Li KO seem conflicting, TFEB genetic modulation experiments in the literature are apparently more consistent toward a protective role against steatosis." (PMID 33937257, 2021). "On contrary to acute supplementation, chronic fat supplementation resulted in steatosis characterized by low LC3 level in LDs, and a reversal of these circumstances was observed upon hepatic ATG7 restoration (L.)." (PMID 34777688, 2021). "Gene expression of autophagy-like proteins was higher in the disease states: ATG7 was higher in NASH in comparison to HC, and ATG5 was higher in steatosis when compared to HOC." (PMID 34869521, 2021). "Overexpression of autophagy-related 7 (Atg7) or Atg14, key autophagy mediators, eliminates steatosis in high fat diet (HFD)-fed mice, while specific deletion of Atg7 gene in the liver alters TAG secretion and increases hepatic lipid contents." (PMID 33372630, 2020). "Intriguingly, hepatic mRNA levels of JMJD3, TFEB, ULK1, ATG7, and ATGL, were all decreased in both simple steatosis and advanced NASH-fibrosis patients compared to normal subjects." (PMID 32042044, 2020). "Deletion of Yap in Atg7/Yap DKO mice reduced hepatocyte size and significantly improved portal and lobular inflammation, ductular reaction, steatosis, and fibrosis in Atg7/Yap DKO mice." (PMID 30470740, 2018). "The total number of IFNγ producing lymphocytes was unaltered between Atg7f/f and Lck-Cre Atg7f/f mice, suggesting that Atg7 deficiency in T cells causes an increase in the percentage of hepatic IFNγ producing T cells but not in the total number of IFNγ producing cells prior to steatosis development." (PMID 30619297, 2018). "While modulating ATG7 expression in adult obese mice showed a negative correlation with steatosis development, an experiment using mice born with depleted hepatic ATG7 showed the opposite effect." (PMID 33937257, 2021). "Acute alcohol binge exacerbated injury and steatosis in Atg5-deleted but not Atg7-deleted livers." (PMID 31614437, 2019). "Systemic Atg7 ablation reduced liver protein synthesis and increased liver injury in vehicle-injected mice but did not further reduce liver protein synthesis, exacerbate steatosis or liver injury, or alter energy expenditure following 5 days of asparaginase exposure." (PMID 39798881, 2025).
anemia (12 papers, 2012 to 2024). A reduction in the number of red blood cells, the amount of hemoglobin, and/or the volume of packed red blood cells. "While the molecular mechanisms of organelle clearance in erythropoiesis are not well understood, it is known that targeted deletion of autophagy genes, including Ulk1, Fip200, and Atg7 causes defective erythroid differentiation and anemia." (PMID 36142738, 2022). "In a mouse model, Atg7 knockout in HSCs led to accumulation of mitochondria with an altered mitochondrial membrane potential in erythrocytes, causing cell death and anemia, similar to the MDS phenotype." (PMID 34445246, 2021). "Mice lacking the autophagy gene Atg7 in the hematopoietic system suffer from severe anemia, and Atg7‐deficient erythrocytes accumulate damaged or dysfunctional mitochondria with altered membrane potential." (PMID 33438778, 2021). "Autophagy impairment had a negative impact on the differentiation of HSCs into mature white and red blood cells, with Atg7-deficient mice displaying reduced myeloid and lymphoid progenitors, as well as severe anemia." (PMID 34445246, 2021). "In a hematopoietic specific and inducible Atg7 knockout mouse model (Vav-iCre:Atg7fl/fl), loss of Atg7 resulted in severe anemia and eventual lethality at 8–14 weeks of age." (PMID 32195258, 2020). "In the mice model to knockout the autophagy gene Atg7 in HSC, mitochondria accumulated in Atg7−/− erythrocytes with changed ΔΨm causing cell death and anemia which was similar to the MDS phenotype." (PMID 29967662, 2018). "The role of Atg7 in regulating mitochondrial clearance in reticulocytes was demonstrated in Atg7−/− mice, which presented with anemia and increased numbers of reticulocytes in blood circulation." (PMID 36142738, 2022). "Atg7 deletion in mice leads to the development of severe anemia, with erythroblasts accumulating damaged mitochondria with an altered membrane potential, a phenomenon that eventually leads to cell death." (PMID 34445246, 2021). "Vav-Atg7−/− mice generated using Atg7 Flox/Flox and Vav-iCre mice have been reported to show severe anemia and shortened lifespans." (PMID 25689426, 2015). "It has been shown that half of Atg7−/− fetal liver cell-transplanted mice die, and the surviving mice display anemia, reticulocytosis, and lymphopenia." (PMID 25689426, 2015). "Notably, rapamycin treatment alleviated the key symptoms typically observed in atg7 KO mice, such as anemia in long bones and splenomegaly." (PMID 37614038, 2024). "A recent study showed that when Atg7 was deleted from erythroid progenitors of wild-type and mtDNA-mutator mice, the genetic disruption of autophagy did not cause anemia in wild-type mice but accelerated the mitochondrial respiration decline and induced macrocytic anemia in the mtDNA-mutator mice." (PMID 25689426, 2015). "Knock out of the autophagic regulators, ULK1, Atg4, Atg7, or FIP200, or mitophagy-specific receptor, NIX, inhibited erythropoiesis leading to anemia in mice while inducing myeloid expansion." (PMID 30546074, 2019). "Atg7 is an essential autophagy gene and mice lacking this gene develop severe anemia as Atg7−/− erythrocytes tend to cumulate impaired mitochondria with altered membrane potential, causing cell death." (PMID 36769414, 2023). "Using mice lacking the essential autophagy gene ATG7 in the hematopoietic system, which develop severe anemia and lymphopenia, ATG7−/− erythrocytes and mature T lymphocytes were found to accumulate damaged mitochondria with altered membrane potential, ultimately leading to cell death." (PMID 22713507, 2012).